CERS6 (ceramide synthase 6)
Diseases named in the same sentence as CERS6 in open-access papers (continued):
Sharing a sentence is not in itself a finding about the gene and the disease.
Insulin resistance (38 papers, 2015 to 2025). Increased resistance towards insulin, that is, diminished effectiveness of insulin in reducing blood glucose levels. "Cers6 encodes ceramide synthase 6 that is responsible for synthesizing C16:00 ceramides, a sphingolipid that is characterized as a pathological driver for insulin resistance." (PMID 35700043, 2022). "One prominent example describes a compensatory up‐regulation of CerS6‐derived increase of C16:0 Cer in haplodeficient CerS2 mice, which mediated susceptibility to diet‐induced steatohepatitis and insulin resistance." (PMID 31692231, 2020). "Insulin resistance caused by a HFD is alleviated by CerS5 or CerS6 gene deletion, which prevents C16 ceramide synthesis in liver and adipose tissue." (PMID 30131496, 2018). "On the other hand, CerS6 deficiency-induced suppression of C16:0 ceramide in mice protects against insulin resistance." (PMID 25993337, 2015). "Notably, the expression of Cers6 is particularly linked to C16:0 ceramide levels and insulin resistance." (PMID 38192209, 2024). "Interestingly, MFF exhibits binding specificity towards CerS6-derived sphingolipids versus diacylglycerols (DAGs), which are also associated with mitochondrial fission events and are known to promote insulin resistance, but likely via a different mechanism." (PMID 35789435, 2022). "In further support of the therapeutic potential of inhibiting CerS6, ablation of the protein’s expression in an obese insulin resistance mouse model led to improved body fat, oral glucose tolerance and insulin sensitivity." (PMID 39528795, 2025). "Previous evidence indicates that CerS6-dependent mitochondrial C16:0 ceramide is involved in regulating mitochondrial dynamics and insulin resistance in obese rats." (PMID 38431645, 2024). "Genetic mouse studies suggest that the specific sphingolipid C16:0 ceramide produced by CerS6 represents a critical player for the onset of insulin resistance." (PMID 36671552, 2023). "Ceramide synthase 6 (CERS6) alleviates insulin resistance, increases systemic energy expenditure, and maintains glucose homeostasis by improving β-oxidation capacity in liver and brown adipose tissues." (PMID 38028584, 2023). "Cers6 inhibition, stemming from Cers6 knockout or Cers6 knockdown, suppresses C16:00 ceramide production and protects against steatosis and insulin resistance in ob/ob and dietary obese mice." (PMID 35700043, 2022). "In a study performed in mice and humans, the RNA expression of CERS6 and C16:0 was higher in visceral and subcutaneous adipose tissue of obese humans, and the increment of CERS6 expression correlates with insulin resistance." (PMID 35269861, 2022). "Substantial differences exist between CerS5- and CerS6-derived C16:0 ceramides in the liver, as only reducing the latter in mice prevents the development of diet-induced insulin resistance and hepatic steatosis." (PMID 35789435, 2022). "had also demonstrated that human white adipose tissue expression of CerS6, responsible for the production of C16:0 ceramides, strongly correlated with key metabolic indices such as insulin resistance, BMI, and whole-body fat mass." (PMID 34385976, 2021). "In obese humans and HFD-fed mice, abundance of C16:0 ceramide and CerS6 expression is increased in adipose tissue, and the latter was demonstrated to be significantly correlated with insulin resistance in humans." (PMID 32455838, 2020). "A study investigated a role for C16-ceramide produced by CerS6 (using CerS6 KO mice) in the progression of muscle insulin resistance." (PMID 32849282, 2020). "They demonstrated that levels of CerS6 were increased in visceral and subcutaneous adipose tissue of obese humans, correlating positively with BMI and insulin resistance." (PMID 32849276, 2020). "Obese humans presented elevated CERS6 mRNA expression and Cer C14:0, C16:0, C16:1, C18:0, C18:1, and C22:1 levels in adipose tissue compared to lean subjects, and a correlation between increasing CERS6 expression and insulin resistance." (PMID 31330872, 2019).
Insulin resistance (continued). "First, overexpression of CerS6 is known to enhance long-chain C16:0 ceramide generation and promote the development of type 2 diabetes and insulin resistance in mice and humans." (PMID 31067249, 2019). "Prior analyses of CerS6-KO mice demonstrated that C16-Cer promotes HFD-induced hepatic insulin resistance and fatty liver disease." (PMID 27010944, 2016). "In line with this notion, CerS6 was recently highlighted as a promising therapeutic target in metabolic disorders including glucose intolerance and insulin resistance." (PMID 25766330, 2015). "In line with this, cell-specific deficiency in CerS5- and CerS6- derived C16:0 failed to prevent insulin resistance in obese mice." (PMID 36671552, 2023). "Studies using genetically modified mice, lacking the gene encoding ceramide synthase 6 (CerS6), that specifically synthesizes palmitoyl-ceramide, have shown that C16:0-Cer plays a particularly important role in hepatic insulin resistance." (PMID 31842461, 2019). "CerS6 mRNA expression and C16:0 ceramide levels were found elevated in the white adipose tissue (WAT) of 439 obese subjects, and this increase was correlated with insulin resistance, body-fat content and hyperglycemia." (PMID 36671552, 2023). "In liver-specific CerS6 knockout mice, researchers found that mitochondrial β-oxidation and hepatic lipid metabolism levels were significantly increased in BAT, which not only improved energy supply but also reduced hepatic steatosis and insulin resistance." (PMID 36594091, 2023). "The authors clearly showed that the binding of CerS6-derived C16:0 ceramide with mitochondrial fissure factor (Mff) leads to the recruitment of dynamin-like protein 1 (DRP1) to the mitochondrial surface, stimulating mitochondrial fission and leading to insulin resistance." (PMID 37762318, 2023). "It is known that high CerS6 expression in the adipose tissue of obese humans is essential for the formation of unfavorable C16:0 ceramide, which is correlated with the development of insulin resistance in adipocytes, but not the whole body." (PMID 35628194, 2022).
lung carcinoma (12 papers, 2020 to 2025). "The ceramide synthase encoded by the gene CERS6 was shown to be required for cell migration and metastasis in lung cancer." (PMID 35631574, 2022). "Here, we analysed sphingolipid metabolic genes regarding their lung cancer‐associated expression profiles, which revealed CERS6 as a pivotal protein for lung cancer progression." (PMID 32902157, 2020). "Analysis of another publicly available lung cancer data set showed similar results, with expression levels of CERS6 well associated with prognosis." (PMID 32902157, 2020). "Based on the present results, we propose that cancer cells are associated with miR‐101 reduction and CERS6 overexpression, alterations that promote metastasis in lung cancer cases." (PMID 32902157, 2020). "Several studies have indicated that CERS6 promotes lamellipodia formation of cells, which is essential for lung cancer migration and metastasis." (PMID 41203639, 2025). "CERS6 plays a crucial role in the progression of multiple types of cancer, including lung cancer, pancreatic cancer, gastric cancer, breast cancer, and ovarian cancer." (PMID 41203639, 2025). "They showed that overexpressed CERS6 in lung cancer synthesizes a bioactive lipid called C16 ceramide, which activates the intracellular protein kinase, RAC1 complex." (PMID 37758931, 2023). "Gene expression analysis of NSCLC tissues and lung cancer cell lines revealed an increased expression of ceramide synthase gene (CERS6)." (PMID 35159223, 2022). "Taken together with results in prior studies, our findings are consistent with the idea that miR‐101 has an onco‐suppressive function and also suggest activity of the miR‐101‐ CERS6 pathway contributes to lung cancer pathogenesis." (PMID 32902157, 2020). "Recent studies have found that CERS6 has important roles in lung cancer migration and metastasis, which proves that the miR-101-CERS6 pathway can be targeted, with potential benefits provided for affected patients." (PMID 33262947, 2020). "Based on these findings, we consider that ceramide synthesis by CERS6 has important roles in lung cancer migration and metastasis." (PMID 32902157, 2020). "Some reports have suggested that overexpressed CERS6 promoted cancer invasion in lung cancer." (PMID 37758931, 2023). "Moreover, knockdown of the CERS6 gene attenuated the metastatic potential of lung cancer cells in mice, supporting the relevance of ceramide in lung cancer migration and metastasis." (PMID 35159223, 2022). "Moreover, CerS6 expression is increased in breast tumors, induces cell death in lung cancer cells, is elevated in breast tumors, and protects from graft-versus-host disease in a mouse model of leukemia." (PMID 33048123, 2020). "In accord with those findings, CERS6 and LASP1 were found to co-localize on lamellipodia in several lung cancer cell lines." (PMID 37345118, 2023). "The present results provide evidence that CERS6, LASP1, and actin form a ternary complex in various lung cancer cell lines." (PMID 37345118, 2023). "Ceramide synthesis by Ceramide Synthase 6 (CERS6) is required for cell migration and metastasis in lung cancer." (PMID 36497343, 2022). "In previous studies, Y-box sequence, as a cis-acting element, up-regulated ceramide synthase 6 through the transcriptional regulation of YBX1 to promote lamellipodia formation as well as migration activity, and up-regulated TGFBR1 to promote the stemness and EMT of lung cancer cells." (PMID 34976785, 2021).
breast carcinoma (11 papers, 2015 to 2025). "In addition, IGF2BP3 promotes CERS6 mRNA stability, which is associated with increased expression of CERS6 and a number of malignant behaviors of breast cancer mediated by CERS6." (PMID 33228740, 2020). "In support, recent findings indicate that downregulation of CERS6 in breast cancer cells in vitro resulted in enhanced membrane fluidity and stimulated cell migration." (PMID 26967245, 2016). "However, it was not tested whether adipose tissue metabolism or adipokines are involved in the regulation of CerS6 and mTOR signaling in breast cancer tissues." (PMID 38698424, 2024). "In human breast cancer, the mRNA expression levels of CERS2, CERS4, and CERS6 and their respective products, C16-, C24-, and C24:1-ceramides, are increased." (PMID 37885013, 2023). "High level of CerS6 decreased phosphorylation of Akt and ERK in MCF-7 breast cancer cells." (PMID 38698424, 2024). "Of note, changes in CerS6 expression in human breast cancer cells do not alter the expression of the epithelial (E-cadherin) and mesenchymal (vimentin) markers, indicating that CerS6 per se does not control EMT." (PMID 27551437, 2015).
head and neck squamous cell carcinoma (11 papers, 2018 to 2025). A squamous cell carcinoma that arises from any of the following anatomic sites: lip and oral cavity, nasal cavity, paranasal sinuses, pharynx, larynx, and salivary glands. "Selective activation of ATF-6 in response to CERS6/C16 ceramide down-regulation protects head and neck squamous cell carcinoma cells from ER stress-induced apoptosis by preventing ER/Golgi [Ca2+] depletion and CHOP activation." (PMID 41203639, 2025). "The CERS6/C16-ceramide induces apoptosis in human head and neck squamous cell carcinoma by the endoplasmic ER-mediated ATF6/CHOP response pathway." (PMID 41203639, 2025). "For example, ceramide C16 produced by ceramide synthase (CerS6) has been shown to play an important role in protecting head and neck squamous cell carcinomas (HNSCC) against apoptosis mediated by stress endoplasmic reticulum (ER)." (PMID 31801274, 2019). "For example, in head and neck squamous cell carcinoma (HNSCC), while ceramide synthase 1–generated C18-ceramide inhibits its tumor growth, ceramide synthase 6–mediated C16-ceramide induces its tumor growth." (PMID 38599378, 2024). "However, the opposite effect could also be seen in head and neck squamous cell carcinoma where knockdown of CerS6 and depletion of its product C16:0-ceramide induced UPR and subsequent apoptosis through decreased ER Ca2+, fusion of the ER and Golgi, and activation of ATF6 signaling." (PMID 39608570, 2024). "For example, CerS1 and CerS6 which generate C18- and C16-ceramides respectively were shown to have both pro-apoptotic and pro-survival roles in head and neck squamous cell carcinoma (HNSCC)." (PMID 38720356, 2024). "For example, CerS1 generates C18-ceramide, mediating cell death and tumor suppression in acute myeloid leukemia (AML) and head and neck squamous cell carcinoma (HNSCC), while CerS6 has an antiapoptotic role in ER stress responses and produces mainly C16-ceramide." (PMID 32121501, 2020).
colon carcinoma (10 papers, 2017 to 2024). "Overexpression of CerS2 and co-expression with CerS6 or CerS4 in colon cancer cells have been shown to promote proliferation, whereas overexpression of CerS4 and CerS6 had rather anti-proliferative effects." (PMID 38635059, 2024). "In human colon cancer tissue, CerS6 expression rather increases, whereas CerS5 expression decreases especially in late-stage colon cancer." (PMID 38635059, 2024). "It has been reported that overexpression of CERS4 and CERS6 in colon cancer cells induced the production of short-chain ceramides (C16: 0, C18: 0 and C20: 0 ceramides), weakened cell proliferation and promoted apoptosis." (PMID 37758931, 2023). "Overexpression of CERS4 and CERS6 in breast and colon cancer cells, leading to an increase in short (C16:0) and long-chain ceramides (C18:0 and C20:0), inhibited cell proliferation and increased apoptosis." (PMID 33568634, 2021). "The increase of CerS6 might be due to an enhanced expression of the long noncoding RNA (lncRNA) ceramide synthase 6 antisense RNA1 (CerS6 AS1), which leads to an enhanced stability of CerS6 mRNA and has tumour-promoting activities in colon cancer." (PMID 38635059, 2024). "However, overexpression or induction of CerS6 in human colon cancer cells has rather anti-proliferative and pro-apoptotic effects." (PMID 38635059, 2024). "However, CerS6 is upregulated in colon tumour tissue, which may be related to the increased requirement of sphingolipids for membrane assembly in rapidly proliferating tumour cells." (PMID 38635059, 2024). "In colon cancer cells with deficiency in CerS6 expression, Caspase-3 may, despite its activation, not be able to translocate to the nucleus, altering late-stage apoptotic signaling." (PMID 37108361, 2023). "Similarly, knockdown of CerS6 in SW480 colon adenocarcinoma cells reduced TRAIL-mediated apoptosis and CerS6 overexpression enhanced TRAIL-mediated cell death in SW620 colon carcinoma cells." (PMID 34063813, 2021). "To determine whether lack of CerS6 can diminishes proliferation in a non-T cell model, we evaluated SW480 colon cancer cells that express a doxycycline-inducible CerS6 shRNA18." (PMID 29138469, 2017).
Glucose intolerance (10 papers, 2015 to 2025). Glucose intolerance (GI) can be defined as dysglycemia that comprises both prediabetes and diabetes. "Furthermore, specific ceramide synthases (in this case, CerS6) have been associated with weight gain and glucose intolerance." (PMID 31212599, 2019). "CerS6 (the enzyme that synthesizes C14 and C16 ceramides) expression was elevated in adipose tissues of obese humans, while there was global ablation of CerS6 in mice protected against glucose intolerance when challenged with a high-fat diet." (PMID 36077094, 2022).
Hepatic steatosis (8 papers, 2016 to 2025). Steatosis is a term used to denote lipid accumulation within hepatocytes. "Liver-specific deletion of CerS6 prevents insulin resistance and hepatic steatosis." (PMID 40057751, 2025). "In addition, induction of liver-specific overexpression of acid ceramidase or deletion of CerS6 expression can also reduce ceramide levels, normalize lipid uptake and sphingolipid metabolism, and improve diet-induced hepatic steatosis." (PMID 36594091, 2023). "Therefore, we speculated that BMP9 might alleviate hepatic steatosis and improve glucose metabolism by downregulating Cers6, Cidea and Fabp4 expression." (PMID 33603666, 2020).
melanoma (8 papers, 2017 to 2026). A malignant, usually aggressive tumor composed of atypical, neoplastic melanocytes. "Human melanomas exhibit low expression of CerS6, the enzyme that generates pro-apoptotic C16-ceramide, and overexpression of acid ceramidase (aCDase), which hydrolyzes ceramide to sphingosine and free fatty acids, relative to normal skin tissue." (PMID 36077841, 2022). "For instance, a low expression of the ceramide synthase 6 (CerS6) in melanoma cells is related to malignant behaviours as demonstrated in WM35, WM451 and SKMEL28 human melanoma cell lines." (PMID 32858889, 2020). "Silencing CerS6 in melanoma cell lines led to increased proliferation and invasion." (PMID 41596686, 2026). "CERs include over 200 distinct molecules generated Via de novo synthesis or cleavage of membrane precursors.The presence of low ceramide synthase 6 (CerS6) expression in melanoma cells has been correlated with malignant behavior, as evidenced in human melanoma cell lines WM35, WM451, and SKMEL28." (PMID 41596686, 2026). "Whether GCS, a ganglioside-metabolising enzyme, CerS6 or SMS2 modulates EMT-TFs in melanoma cells remains to be evaluated." (PMID 32858889, 2020). "However, loss of CerS6 does not universally decrease proliferation as targeting this enzyme results enhanced proliferation in melanoma cells." (PMID 29138469, 2017). "Accordingly, low CERS6 and high ASAH1 in human cutaneous melanoma may contribute to the low ceramide accumulation in melanoma." (PMID 36077841, 2022).